DNAJC28 (DnaJ heat shock protein family (Hsp40) member C28)
Description:
May have a role in protein folding or as a chaperone.
Synonyms: C21orf55; C21orf78
Tractability: PROTAC: ubiquitination databases record sites on it.
Gene: Protein-coding gene on chromosome 21 (33,486,096 to 33,491,749, reverse strand). Ensembl gene ENSG00000177692.
Subcellular location (Human Protein Atlas): Centrosome; Nucleoplasm; Cytosol; Nuclear bodies
Gene Ontology:
Molecular function: protein binding
Biological process: temperature homeostasis
Genetic constraint (gnomAD): Loss-of-function variants: 23 observed, 33.51 expected, observed/expected ratio (o/e) 0.69, 90% interval 0.49 to 0.97. The upper end of that interval is the gene's LOEUF score, 0.97, which puts it in group 4 of 6, group 1 being the genes least tolerant of losing a copy. Missense variants: 438 observed, 466.22 expected, observed/expected ratio (o/e) 0.94, 90% interval 0.87 to 1.02. Synonymous variants: 120 observed, 150.08 expected, observed/expected ratio (o/e) 0.8, 90% interval 0.69 to 0.93.
Homologues: Orthologues: chimpanzee DNAJC28 (99% identical), macaque DNAJC28 (96% identical), dog DNAJC28 (84% identical), rabbit DNAJC28 (81% identical), pig DNAJC28 (81% identical), guinea pig DNAJC28 (79% identical), rat Dnajc28 (73% identical), mouse Dnajc28 (72% identical), tropical clawed frog dnajc28 (52% identical), zebrafish dnajc28 (44% identical), Drosophila melanogaster CG43322 (31% identical). Paralogues in human: COG4 (18% identical).
Diseases named in the same sentence as DNAJC28 in open-access papers:
DNAJC28 is named in the same sentence as 8 diseases in open-access papers, as found by Europe PMC text mining. Sharing a sentence is not in itself a finding about the gene and the disease. The quoted sentences say what the papers report.
Alzheimer disease (1 paper, 2021). A progressive, neurodegenerative disease characterized by loss of function and death of nerve cells in several areas of the brain leading to loss of cognitive function such as memory and language. "Dnajc28 was previously implicated in the pathogenesis of neurodegenerative diseases, such as Alzheimer’s Disease and Parkinson’s Disease, possibly as a protective protein that is expressed in high level in the setting of local injury or toxicity." (PMID 34440346, 2021).
colon cancer (1 paper, 2022). "Furthermore, the roles of VSIG10 and DNAJC28, which may be involved in stem cell function, in IBD and colon cancer, remain unknown." (PMID 35323693, 2022).
lupus (1 paper, 2021). "Of those, the most notable are Dnajc28, Syne2 (synaptic nuclear envelope 2) that are upregulated in the MRL/lpr model compared with both Fn14ko and MRL/+, as well as transthyretin (Ttr) that is downregulated in the lupus-prone mice compared with both controls." (PMID 34440346, 2021).
infection (2 papers, 2014 to 2016). The state of being infected such as from the introduction of a foreign agent such as serum, vaccine, antigenic substance or organism. "For instance, Dnaja2, Dnajb2, Dnajb12a, Dnajb12b, Dnajb14, Dnajc5ab, Dnajc5gb, Dnajc7, Dnajc16, and Dnajc26 were up-regulated only at 3 days after infection, but not at 14 days after infection; similarly, Dnajc28 was up-regulated only at 14 days after infection, but not at 3 days after infection." (PMID 25542027, 2014).
cancer (1 paper, 2020). A tumor composed of atypical neoplastic, often pleomorphic cells that invade other tissues. "Of interest, 16 (16/22, 72.7%) of them are HSP40 family members, including DNAJC28, which was associated with 10 hallmarks across 8 cancers; DNAJC19, which was associated with 8 hallmarks across 5 cancers; and DNAJC30, which was associated with 6 hallmarks across 5 cancers." (PMID 33225964, 2020).
DNAJC28 also shares sentences with these, for which no sentence is quoted: bacterial infections (1 paper); neurodegenerative disease (1); Parkinson disease (1).